PIGQ (phosphatidylinositol glycan anchor biosynthesis class Q)
Description:
Part of the glycosylphosphatidylinositol-N-acetylglucosaminyltransferase (GPI-GnT) complex that catalyzes the transfer of N-acetylglucosamine from UDP-N-acetylglucosamine to phosphatidylinositol and participates in the first step of GPI biosynthesis.
Synonyms: GPI1; hGPI1; DEE77; EIEE77; GPIBD19; MCAHS4; c407A10.1
Tractability: Antibody: UniProt predicts a signal peptide or a membrane-spanning region. PROTAC: ubiquitination databases record sites on it.
Gene: Protein-coding gene on chromosome 16 (566,995 to 584,120, forward strand). Ensembl gene ENSG00000007541.
Subcellular location: Membrane
Subcellular location (Human Protein Atlas): Golgi apparatus; Vesicles; Nucleoplasm
Pathways (Reactome):
Metabolism of proteins: Synthesis of glycosylphosphatidylinositol (GPI)
Gene Ontology:
Molecular function: protein binding; phosphatidylinositol N-acetylglucosaminyltransferase activity
Biological process: GPI anchor biosynthetic process; carbohydrate metabolic process
Cellular component: endoplasmic reticulum membrane; glycosylphosphatidylinositol-N-acetylglucosaminyltransferase (GPI-GnT) complex; endoplasmic reticulum; membrane
Genetic constraint (gnomAD): Loss-of-function variants: 50 observed, 48.86 expected, observed/expected ratio (o/e) 1.02, 90% interval 0.81 to 1.29. The synonymous counts are far from expectation, so gnomAD's model fits this gene poorly and the ratio says little. Missense variants: 738 observed, 694.43 expected, observed/expected ratio (o/e) 1.06, 90% interval 1 to 1.13. Synonymous variants: 383 observed, 310.47 expected, observed/expected ratio (o/e) 1.23, 90% interval 1.13 to 1.34.
Gene-disease validity (ClinGen):
ClinGen rates the evidence that PIGQ causes each of these diseases.
developmental and epileptic encephalopathy, 77 (autosomal recessive): Definitive.
Homologues: Orthologues: chimpanzee PIGQ (91% identical), macaque PIGQ (89% identical), pig PIGQ (87% identical), dog PIGQ (86% identical), rat Pigq (85% identical), guinea pig PIGQ (84% identical), mouse Pigq (84% identical), rabbit PIGQ (74% identical), tropical clawed frog pigq (64% identical), zebrafish pigq (63% identical), Drosophila melanogaster PIG-Q (22% identical), Caenorhabditis elegans pigq-1 (15% identical).
Diseases named in the same sentence as PIGQ in open-access papers:
PIGQ is named in the same sentence as 25 diseases in open-access papers, as found by Europe PMC text mining. Sharing a sentence is not in itself a finding about the gene and the disease. The quoted sentences say what the papers report.
developmental delay (2 papers, 2015 to 2018). "For example, PIGQ is involved in early steps of GPI anchor biosynthesis and deficiencies in this pathway are linked to Mabry syndrome marked by severe developmental delays and intellectual disability, autosomal recessive intellectual disability and intractable epilepsy." (PMID 25849048, 2015).
Epileptic encephalopathy (2 papers, 2014 to 2020). A condition in which epileptiform abnormalities are believed to contribute to the progressive disturbance in cerebral function. "We investigated seven children from six families to expand the phenotypic spectrum associated with an early infantile epileptic encephalopathy caused by biallelic pathogenic variants in the phosphatidylinositol glycan anchor biosynthesis class Q (PIGQ) gene." (PMID 32588908, 2020). "Using a targeted resequencing approach, we screened KCNT1, PIGQ, CBL and CSNK1G1 in a large cohort of epileptic encephalopathy cases from Australia." (PMID 24463883, 2014).
congenital disorder of glycosylation (1 paper, 2025). Congenital disorder of glycosylation (CDG) is a fast growing group of inborn errors of metabolism characterized by defective activity of enzymes that participate in glycosylation (modification of proteins and other macromolecules by adding and processing of oligosaccharide side chains). "Biallelic causal variants in the PIGQ gene (OMIM: * 605754) are associated with a type of disorder of glycosylphosphatidylinositol biosynthesis (PIGQ-congenital disorders of glycosylation (CDGs), also called multiple congenital anomalies-hypotonia-seizures syndrome 4 (MCAHS4, OMIM: # 618548)." (PMID 40718141, 2025).
early-onset epilepsy (1 paper, 2021). "A variant on CFA6 (CFA6:39,977,184 G>A) was located in the intron region of PIGQ gene, which has been reported to be the causative gene for human early-onset epilepsy." (PMID 34368281, 2021). "It has been reported that PIGQ is associated with the neurologic disorder of severe early-onset epilepsy." (PMID 34368281, 2021).
epilepsy (1 paper, 2025). A brain disorder characterized by episodes of abnormally increased neuronal discharge resulting in transient episodes of sensory or motor neurological dysfunction, or psychic dysfunction. "Intriguingly, similar digestive symptoms as well as epilepsy have been found in a cohort of patients with variants in PIGQ." (PMID 39825393, 2025). "Variants in PIGQ could therefore contribute to epilepsy and indirectly to gastrointestinal abnormalities through a multi-step pathway." (PMID 39825393, 2025).
infantile epileptic encephalopathy (1 paper, 2023). an epileptic condition characterized by epileptiform abnormalities associated with progressive cerebral dysfunction. "Indeed, impaired PIGQ variants result in infantile epileptic encephalopathy." (PMID 37848418, 2023).
polymicrogyria (1 paper, 2024). A developmental brain abnormality characterized by an excessive amount of small convolutions on the surface of the brain and cognitive dysfunction. "One individual (Patient F-33), with pathogenic variants in PIGQ, had perisylvian polymicrogyria." (PMID 38456468, 2024).
rhabdomyolysis (1 paper, 2025). Necrosis or disintegration of skeletal muscle often followed by myoglobinuria. "Bioinformatic reanalysis of the WES data has been done in P1, but no other genetic cause (except variants in the PIGQ gene) has been found to be responsible for rhabdomyolysis." (PMID 40718141, 2025).
cancer (1 paper, 2022). A tumor composed of atypical neoplastic, often pleomorphic cells that invade other tissues. "The top 100 JMJD8 coexpressed genes in pan-cancer were analyzed on GEPIA2.0, and the top 5 genes (C16ORF58, IFT140, ITFG3, PIGQ, and WDR24) showed high correlations with JMJD8 in the majority of cancer types." (PMID 35898493, 2022).
PIGQ also shares sentences with these, for which no sentence is quoted: tumor (6 papers); genetic diseases (2); anaemia (1); autosomal recessive intellectual disability (1); clear cell renal cell carcinoma (1); epileptic seizures (1); Hyperglycemia (1); hypertrophy (1); Immunodeficiency (1); infection (1); insomnia (1); Intellectual disability (1); Mabry syndrome (1); macroglossia (1); neurologic disorder (1); schizophrenia (1).